BDNF (brain derived neurotrophic factor)
Diseases named in the same sentence as BDNF in open-access papers (continued):
Sharing a sentence is not in itself a finding about the gene and the disease.
Stroke (continued). "Notably, a positive correlation between plasma BDNF levels at 4 h post-embolization and the degree of embolization was also found after pooling the groups “stroke 4 h”, stroke 24 h” and stroke 8 d” (n = 30, rs = 0.364, p = 0.024)." (PMID 22195050, 2011). "However, it is possible that the first blood sample was collected too late in stroke patients (10.7 h±7.6 for SD vs 4 h post-embolization), thus missing the opportunity to detect stroke severity-dependent changes in plasma BDNF levels in patients." (PMID 22195050, 2011). "Therefore, the effect of stroke on circulating BDNF can only be assessed by comparing BDNF levels in stroke patients with those in healthy subjects." (PMID 22195050, 2011). "Forced treadmill exercise was shown to elevate serum corticosterone concentration, which probably consequently reduced BDNF concentration in the rat brain, and it might diminish the beneficial effect of training on persons after stroke." (PMID 21347437, 2011). "Circulating BDNF levels do not mirror brain BDNF levels after stroke, and severe stroke is associated with high plasma BDNF in the very acute stage." (PMID 22195050, 2011). "BDNF levels were measured in the whole brain and in the blood (plasma and serum) collected from the jugular vein in rats subjected to different severities of unilateral embolic stroke." (PMID 22195050, 2011). "Brain-derived neurotrophic factor (BDNF) can decrease infarct volume and improve neurological outcome either by exogenously supplied or overexpression in vivo using genetic methods in experimental stroke." (PMID 21490702, 2010). "Moreover, they both minic BDNF by exhibiting robust neuroprotective effect in stroke, neuroexcitotoxicity, and vestibular ganglia survival assays." (PMID 20644624, 2010). "Furthermore, exercise aids recovery from brain injuries such as stroke by enhancing the expression of neurotrophic factors like Brain-Derived Neurotrophic Factor (BDNF), promoting growth, survival, the differentiation of neurons, angiogenesis, and stimulating anti-apoptotic pathways." (PMID 41562755, 2026). "To explore underlying mechanisms, we measured serum levels of Brain-Derived Neurotrophic Factor (BDNF), a key marker of neuroplasticity, and pro-inflammatory cytokines Tumor Necrosis Factor-alpha (TNF-α) and Interleukin-6 (IL-6), which are implicated in post-stroke neural injury and repair." (PMID 40904820, 2025). "Activity-dependent BDNF release in particular plays a key role in mediating and promoting synaptic plasticity in cortical cells, hippocampal cells and beyond, which indicates that BDNF could be a key factor in learning and memory functions involved in stroke pathophysiology and prognosis." (PMID 40658687, 2025). "However, the literature data on BDNF and stroke are varied and discordant." (PMID 41447407, 2025). "Stroke triggers a hypoxic environment, and BDNF expression in the brain may be downregulated." (PMID 40994138, 2025). "In conclusion, our study reveals that reduced BDNF levels in AIS patients with T2DM are associated with the formation of denser, less permeable, fibrin-rich thrombi, which may contribute to thrombolysis resistance and worse stroke outcomes." (PMID 41280373, 2025). "Disentangling the histological underpinnings of these imaging biomarkers, particularly by independently analyzing cortical thickness and area, could provide more specific insights into the therapeutic potential of targeting pathways such as BDNF/TrkB to ameliorate language impairment after stroke." (PMID 41181681, 2025). "Additionally, variations in the p11/tPA/BDNF pathway affect depressive outcomes following stroke." (PMID 40529498, 2025). "The study suggests that typical BDNF may enhance neural activity related to language processing and semantic memory, contributing to better outcomes in aphasia patients and enhancing neuroplasticity and recovery after stroke." (PMID 40492169, 2025).
Stroke (continued). "For example, combining isorhamnetin with brain-derived neurotrophic factor in hydrogel formulations could promote neurogenesis and functional recovery after stroke, potentially leveraging the unique properties of both compounds to maximize therapeutic benefits." (PMID 40277696, 2025). "It remains unclear how molecules that potentially drive better recovery following stroke—such as brain-derived neurotrophic factor (BDNF) and vascular endothelial growth factor (VEGF)—mediate neuroplasticity following HH exposure during recovery from cerebral ischemic injury." (PMID 41465442, 2025). "Exercise could resist the decline in BDNF levels post-stroke." (PMID 40520612, 2025). "We retrospectively analyzed data from 77 participants with post-stroke aphasia from three recent or ongoing studies that included both repeated standardized picture naming assessments in the acute, subacute, and chronic phases and brain-derived neurotrophic factor genotyping." (PMID 40658687, 2025). "Partial NMDA receptor antagonism with ketamine could, therefore, attenuate this pathological glutamatergic drive, shift transmission toward AMPA-mediated pathways, enhance BDNF-dependent synaptogenesis, and facilitate functional reorganization of post-stroke networks." (PMID 41425807, 2025). "Investigating the interactions between BDNF genotypes and specific rehabilitation approaches and adjuvants, such as non-invasive brain stimulation could provide further insights into personalized and optimized post-stroke aphasia treatment." (PMID 40658687, 2025). "One study examined eight weeks of combining HIIT with strength training, and another one conducted a three-month study on stroke patients; both found decreases in BDNF, likely due to prolonged physiological stress, which may override the neurotrophic benefits of exercise under certain conditions." (PMID 39851402, 2024). "Indeed, stroke-related changes in neuroplasticity appear to be directly related to BDNF levels." (PMID 39224579, 2024). "On the other hand, CANA demonstrates an outstanding neuroprotective effect in stroke that is realized by means of an alternative mechanism rather than the influence on astroglia that can involve a direct influence on neuronal survival, including the BDNF-mediated mechanism." (PMID 39767704, 2024). "The elevation of BDNF concentration in the cortex could enhance synaptogenesis and dendritic spine development, thereby facilitating cortical functional remodeling in survivors of stroke." (PMID 38816852, 2024). "Thus, peripheral BDNF concentrations may not be correlated with CSF concentrations of BDNF, and assessments of both serum and CSF BDNF concentrations should be evaluated specifically in children after stroke." (PMID 38397427, 2024). "Studies suggest that rTMS may regulate the sleep–wake system by reducing cortical excitability, modulating neurotransmitter activity (such as GABA, 5-HT, and BDNF) and increasing cerebral blood flow, thereby improving sleep quality in stroke patients with sleep disorders." (PMID 39539650, 2024). "Thus, ischemia-induced endogenous Nrf2/HO-1 axis could promote BDNF production that subsequently enhances neurogenesis, leading to improved functional outcomes after stroke." (PMID 39469715, 2024). "Furthermore, upregulation of BDNF has a neuroprotective effect after experimental stroke." (PMID 37153779, 2023). "Thus, it was demonstrated that patients who received rehabilitation procedures starting 3–6 days after the onset of a stroke had better motor functions, psychological profile, and cognitive abilities and, along with this, higher levels of BDNF in blood serum 6 months after the onset." (PMID 36969561, 2023). "Similarly, BDNF was reported to be a valid neuroimmune mediator of stroke that could predict the prognosis of the patients." (PMID 37175644, 2023). "Poststroke BDNF fluctuation may affect the validity of BDNF as a biomarker for stroke diagnosis." (PMID 38137853, 2023).
Stroke (continued). "Indeed, the release of BDNF is dependent on exercise intensity, with exercise-induced increases in BDNF correlated with improvements in cognitive and motor function in both neurologically-intact humans and animal models of stroke." (PMID 38196979, 2023). "Preclinical studies demonstrated that BDNF induces anti apoptotic mechanisms, reducing the size of the lesion and secondary death, promoting synaptogenesis, neuronal plasticity and recovery post stroke; moreover, increase of BDNF concentration in the cortex is related to motor learning after-stroke." (PMID 37719764, 2023). "Early rehabilitation, which starts between 24 and 72 h after stroke, has been shown to reduce the levels of inflammatory cytokines, protect the blood–brain barrier, inhibit apoptosis, promote neurogenesis, and upregulate brain-derived neurotrophic factor levels." (PMID 37287803, 2023). "The level of BDNF in the acute period of ischemic stroke can be considered as a potential biomarker for the recovery of not only motor but also cognitive functions, as well as contribute to the search for additional targeted therapy in the course of stroke prevention." (PMID 36969561, 2023). "In addition to BDNF, dopamine is also related to post-stroke recovery." (PMID 35330487, 2022). "Moreover, Q10 increased the SOD activity and BDNF level in the brain tissue of stroke animals." (PMID 35656440, 2022). "The increased concentration of BDNF in the cerebral cortex may complete synaptogenesis and promote the formation and branching of dendritic spines, thus promoting cortical functional remodeling in stroke patients." (PMID 36138921, 2022). "Hence, therapeutics that can modulate endogenous BDNF signaling in the brain may be useful in the context of stroke." (PMID 34108925, 2021). "Thus, the exact role of BDNF, specifically in serum, in stroke patients is still unclear." (PMID 33809965, 2021). "Finally, a recent line of research is focusing on genetic biomarkers since some genes, in particular, genetic variations of the brain-derived neurotrophic factor (BDNF), catechol-O-methyl transferase polymorphism, and dopamine receptor, have been implicated in stroke recovery and prognosis." (PMID 33897593, 2021). "Finally, after adjusting for other stroke predictors, BDNF-PBMCs predicted functional outcome (OR = 12.4, 95%CI: 1.4–112.2, p = 0.046) and the authors reported a cutoff value of 6.66 ng/mg to predict good functional outcome (mRS = 0–2) (sensitivity/specificity = 48.0%/92.9%, respectively)." (PMID 33809965, 2021). "However, the role of BDNF in recovery from TBI or stroke has been controversial." (PMID 33479258, 2021). "MiR-206 knockdown exosomes attenuated early brain injury by upregulation of BDNF levels after exosome treatment, which gives us an idea that bioengineering exosomes with BDNF could have a positive outcome for brain disorders, including stroke." (PMID 33869170, 2021). "A better understanding of BDNF molecular modulation and its epigenetic regulatory mechanism could impact the management of post-stroke patients, facilitating the selection of a personalized rehabilitation protocol with a greater impact on recovery times, and likely on the reduction of the cost." (PMID 33182716, 2020). "Interestingly, inducing a stroke lesion by itself results in reduced BDNF expression." (PMID 32916851, 2020). "Evidence suggests that progressively intense, aerobic training performed 2 or 3 times per week for at least 8 to 9 weeks could improve walking ability as well as result in a trend towards an increase in resting BDNF levels in people with MS and in other neurological disorders such as stroke." (PMID 31969132, 2020). "Importantly, a hypothermia treatment upregulated the BDNF level in these stroke mice." (PMID 32010477, 2020). "Thus, the BDNF genotype may need to be considered as a factor influencing neuroplasticity and functional recovery in patients with stroke." (PMID 33029116, 2020).
Stroke (continued). "Taken together, these lines of evidence suggest that post-stroke exercise regimens such as the one used in this study may induce neuroplasticity and influence rehabilitative outcomes through the changes they provoke in the BDNF pathway." (PMID 32670026, 2020). "Therefore, the enhanced BDNF and oxytocin signaling after the hypothermia treatment are likely important contributors to the belated and lasting anti-psychological benefits after stroke." (PMID 32010477, 2020). "Hence, capitalizing on the beneficial effects of BDNF in the CNS may be effective for facilitating recovery after stroke." (PMID 33029119, 2020). "In accordance with these results, motor function and protein expression levels of BDNF and TrkB activation were significantly increased by combined rTMS and aerobic exercise, indicating that this approach may be a promising strategy for stroke rehabilitation." (PMID 32210177, 2020). "In the MCAO stroke model, GDX rats treated with T for 10 days starting 24 h after induction of brain ischemia show increased antioxidant effects, as well as increased brain-derived neurotrophic factor (BDNF) levels and neurogenesis, associated with enhanced recovery." (PMID 32605602, 2020). "Moreover, BDNF can promote the activation of astrocytes, and astrocyte-derived exosomes promote axonal elongation and functional recovery after the subacute phase of stroke." (PMID 32937754, 2020). "Therefore, BDNF appears to be a prime candidate for use as a stroke treatment." (PMID 32399020, 2020). "Our previous research supports that a period of post-stroke SI can lead to changes in neurogenesis during stroke recovery, which may be due to changes in the regulation of certain miRNAs that target brain-derived neurotrophic factor (BDNF) and other neurotrophic factors." (PMID 33374156, 2020). "The BDNF-mediated facilitation of reversal learning/cognitive flexibility that was observed in the current study may reflect a reopening of a critical window for functional recovery of cognition after stroke." (PMID 31191635, 2019). "Additionally, Western blot results showed that stress of stroke also stimulated more BDNF secretion in the hippocampus of the ipsilateral hemisphere, and the increased trend of BDNF secretion was dose-dependent after administration of GASP at day 14 (p < 0.001)." (PMID 31191223, 2019). "However, a meta-analysis in non-stroke patients has shown a lack of association between BDNF-196 genotype and serum BDNF levels." (PMID 31359356, 2019). "Finally, we show that this stroke-induced improvement in learning observed in the aged mice was BDNF dependent, as the improvement in learning was blocked following administration of the BDNF decoy, TrkB-Fc." (PMID 31191635, 2019). "Therefore, the most parsimonious explanation for the stroke-induced improvement in cognitive flexibility observed in the current study in aged mice is that BDNF levels are elevated as a result of the stroke, which also fits with TrkB-Fc's ability to dampen this response." (PMID 31191635, 2019). "Therefore, the decrease of serum BDNF concentrations after stroke can be used as a PSD predictor." (PMID 30061860, 2018). "This suggests that although neurogenesis and post-stroke recovery may occur in tandem, this may be coincidental, with recovery being more directly related to the upregulation of a variety of growth-promoting factors such as BDNF and GAP43." (PMID 30050416, 2018). "Additionally, genetic factors such as alterations in the brain-derived neurotrophic factor gene may influence brain plasticity and recovery after stroke." (PMID 28205065, 2017). "Also, it remains unclear whether BDNF serum levels may be used as a biomarker of cognitive training in patients with stroke." (PMID 28859664, 2017). "Therefore, BDNF may be a good candidate to follow stroke development, even in chronic poststroke subjects, where circulating BDNF is very low with respect to controls." (PMID 28373915, 2017).
Stroke (continued). "Additionally, BDNF has been demonstrated to reduce ER stress in neurons and after stroke." (PMID 28640888, 2017). "Additionally, BDNF has been shown to be involved in recovery after stroke." (PMID 28640888, 2017). "The same group demonstrated that rhEPO starting 24 h after experimental stroke in the rat significantly improved functional recovery and enhanced angiogenesis and neurogenesis, which correlated well with increased levels of brain-derived neurotrophic factor (BDNF) and VEGF." (PMID 28703764, 2017). "Moreover, very recent work demonstrated that BDNF treatment leads to a significant increase in the number of proliferating cells, including OPCs, after white matter injury as improved functional recovery after stroke." (PMID 27125783, 2016). "Although it is unknown whether administration of exogenous thyroid hormone in stroke patients improves outcomes, administration of T3 resulted in increased mRNA expression of reelin and brain-derived neurotrophic factor in rats, both of which are important in nervous system regeneration." (PMID 26157487, 2015). "Finally, in cerebral ischemia, Smad1 may mainly function as a downstream effector of canonical BMP signaling, or alternatively, as a mediator of other stroke-induced signaling pathways, such as brain-derived neurotrophic factor (BDNF) or GSK3β signaling." (PMID 26317208, 2015). "A stroke mouse paired with a healthy partner showed enhanced behavioral recovery compared with either isolated mice or a mouse paired with another stroke mouse; these beneficial effects were mediated through brain-derived neurotrophic factor (BDNF) signaling and neurogenesis." (PMID 25870536, 2015). "In addition, to verify whether the time to treatment interval could have affected serum BDNF levels, patients treated 2h after stroke onset were dissociated from patients treated beyond 2h." (PMID 26469350, 2015). "Interestingly, although the AT2R is only sparsely expressed across the total population of microglia, they are abundantly expressed on the cells that produce BDNF, and this phenotype is preserved in stroke, which implies a specific involvement of the AT2R in this cell population." (PMID 24752645, 2014). "However a role for BDNF in long-term functional outcome post-stroke was suggested." (PMID 25470006, 2014). "In addition, increased NGF and BDNF expressions may contribute to the neuroinflammation-induced neuroprotection observed in acute brain injuries and early stages of stroke." (PMID 23651534, 2013). "To determine if our cultured DCs could be engineered for therapeutic delivery we tested human brain-derived neurotrophic factor (hBDNF) as a candidate extracellular cargo, as post-injury delivery of hBDNF protects in stroke models; this effect occurs extracellularly via TrkB receptor binding." (PMID 23613937, 2013). "Thus, the BDNF/TrkB pathway, at least partially, mediates eNOS-/- reduced WM damage after stroke." (PMID 24236179, 2013). "BA treatment following stroke has also been demonstrateed to have antioxidative and antiapoptotic properties that may act by increasing superoxide dismutase, glutathione peroxidase and glutathione, and BDNF expression while reducing caspase-3 activity." (PMID 24381634, 2013). "Thus, in this study using a model of stroke in mice, we investigate whether eNOS impacts WM-damage after stroke and the possible role of BDNF in this process." (PMID 24236179, 2013). "These indirect evidences support that BDNF may enhance the migration of SVZ cells in stroke brains." (PMID 24312581, 2013). "Based on these findings, it could be postulated that BDNF promoter methylation status will be associated with stroke outcomes, although this hypothesis has not been tested yet." (PMID 23240009, 2012). "However, further research into the role of BDNF in stroke patients is indicated." (PMID 23240009, 2012).